CACNA1A (calcium voltage-gated channel subunit alpha1 A)
Description:
Voltage-sensitive calcium channels (VSCC) mediate the entry of calcium ions into excitable cells and are also involved in a variety of calcium-dependent processes, including muscle contraction, hormone or neurotransmitter release, gene expression, cell motility, cell division and cell death. The isoform alpha-1A gives rise to P and/or Q-type calcium currents. P/Q-type calcium channels belong to the 'high-voltage activated' (HVA) group and are specifically blocked by the spider omega-agatoxin-IVA (AC P54282) (By similarity). They are however insensitive to dihydropyridines (DHP).
Synonyms: BI; CACNL1A4; Cav2.1; EA2; APCA; HPCA; FHM; DEE42; EIEE42; MHP; MHP1; SCA6
Tractability: Small molecule: an approved drug acts on it; a structure with a bound ligand is known; a high-quality ligand is known; it belongs to a druggable protein family. Antibody: UniProt places it where antibodies can reach, with high confidence; its Gene Ontology location is reachable by antibodies, with high confidence; UniProt predicts a signal peptide or a membrane-spanning region. PROTAC: ubiquitination databases record sites on it; a small molecule that binds it is known.
Target class: Voltage-gated calcium channel; Ion channel; Voltage-gated ion channel
Gene: Protein-coding gene on chromosome 19 (13,206,442 to 13,624,489, reverse strand). Ensembl gene ENSG00000141837.
Subcellular location: Cell membrane
Subcellular location (Human Protein Atlas): Endoplasmic reticulum
Pathways (Reactome):
Metabolism: Regulation of insulin secretion
Neuronal System: Presynaptic depolarization and calcium channel opening
Gene Ontology:
Molecular function: high voltage-gated calcium channel activity; protein binding; syntaxin binding; voltage-gated calcium channel activity; amyloid-beta binding; monoatomic ion channel activity; voltage-gated calcium channel activity involved in regulation of presynaptic cytosolic calcium levels
Biological process: calcium ion transmembrane transport; cellular response to amyloid-beta; modulation of chemical synaptic transmission; positive regulation of cytosolic calcium ion concentration; response to amyloid-beta; calcium ion import across plasma membrane; chemical synaptic transmission; monoatomic ion transport; regulation of presynaptic cytosolic calcium ion concentration; transmembrane transport
Cellular component: cell projection; cytoplasm; nucleus; plasma membrane; membrane; neuronal cell body; voltage-gated calcium channel complex; dendrite; glutamatergic synapse; postsynaptic membrane; presynaptic active zone membrane
Genetic constraint (gnomAD): Loss-of-function variants: 47 observed, 180.97 expected, observed/expected ratio (o/e) 0.26, 90% interval 0.2 to 0.33. The upper end of that interval is the gene's LOEUF score, 0.33, which puts it in group 1 of 6, group 1 being the genes least tolerant of losing a copy. Missense variants: 2,371 observed, 2,959.9 expected, observed/expected ratio (o/e) 0.8, 90% interval 0.77 to 0.83. Synonymous variants: 1,331 observed, 1,182.5 expected, observed/expected ratio (o/e) 1.13, 90% interval 1.08 to 1.18.
Homologues: Orthologues: chimpanzee CACNA1A (99% identical), dog CACNA1A (96% identical), macaque CACNA1A (95% identical), pig CACNA1A (94% identical), rat Cacna1a (87% identical), mouse Cacna1a (87% identical), tropical clawed frog cacna1a (70% identical), guinea pig CACNA1A (70% identical), zebrafish cacna1ab (68% identical), zebrafish cacna1aa (67% identical), rabbit CACNA1A (60% identical). Paralogues in human: CACNA1B (60% identical), CACNA1E (55% identical), CACNA1C (33% identical), CACNA1D (33% identical), CACNA1S (31% identical), CACNA1F (31% identical), CACNA1I (21% identical), CACNA1H (21% identical), CACNA1G (20% identical), SCN2A (20% identical), SCN3A (20% identical), SCN1A (20% identical), and 14 more.
Diseases named in the same sentence as CACNA1A in open-access papers:
CACNA1A is named in the same sentence as 284 diseases in open-access papers, as found by Europe PMC text mining. Sharing a sentence is not in itself a finding about the gene and the disease. The quoted sentences say what the papers report.
Ataxia (198 papers, 2006 to 2026). Ataxia refers to impaired coordination of voluntary muscle movement. "Episodic ataxia type 2 (EA2) is caused by loss-of-function mutations in CACNA1A, resulting in P/Q-type Ca2+ channel dysfunction in cerebellar Purkinje cells (PCs) causing ataxia and stress-induced dystonia." (PMID 41847229, 2026). "To date, numerous pathogenic variants in the CACNA1A gene have been documented, with links to other ataxias and neurodevelopmental conditions." (PMID 40169779, 2025). "A recent study highlighted that heterozygous loss-of-function variants in the CACNA1A gene not only result in classical ataxia but are also associated with a range of other phenotypes, including epilepsy and intellectual disability." (PMID 40342369, 2025). "Numerous studies have demonstrated encouraging outcomes in using verapamil in managing specific symptoms, such as migraine, ataxia, and episodic syndromes associated with CACNA1A variants." (PMID 40111503, 2025). "Treatment with acetazolamide was initiated due to the known positive effects of carbonic anhydrase inhibitors in cases of CACNA1A-associated ataxia, but was discontinued shortly thereafter because of diarrhea." (PMID 40703772, 2025). "Generation of iPSCs has also been achieved from a patient affected by SCA6, an adult-onset, slowly progressive cerebellar ataxia associated with dysarthria and nystagmus linked to mutations in the gene CACNA1A (calcium voltage-gated channel subunit alpha 1 A)." (PMID 41007684, 2025). "Another interesting gene was CACNA1A, which has been linked to several diseases, including episodic ataxia, cerebellar ataxia, and developmental and epileptic encephalopathy." (PMID 40533913, 2025). "Familial hemiplegic migraine (FHM) episodic ataxia (EA2) and some cases of spinocerebellar ataxia have been linked to point mutations in the CACNA1A gene." (PMID 40111503, 2025). "Mutations in Cacna1a, such as the one found in tottering mice, lead to dysfunction in these channels and are associated with various neurological disorders, including ataxia, epilepsy, and migraines." (PMID 39452036, 2024). "Genetic testing identified a heterozygous variant in the CACNA1A gene, resulting in cervical dystonia and cerebellar ataxia." (PMID 38785745, 2024). "CACNA1A is also known to induce episodic ataxia type 2, suggesting that even missense variants in crucial protein domains can cause ataxia-related symptoms." (PMID 37845370, 2023). "A number of other recessive loss-of-function mutations in Cacna1a (termed tottering, leaner, rolling Nagoya, and rocker) produce a phenotype of ataxia, seizures, and dystonia/dyskinesia in mice." (PMID 35757096, 2022). "CACNA1A-associated epilepsy and ataxia frequently accompany cognitive impairments as devastating co-morbidities." (PMID 35548926, 2022). "CACNA1A-associated disorders, such as epilepsy and ataxia, are frequently accompanied by cognitive impairments." (PMID 35548926, 2022). "Unfortunately, we did not have parental samples to test for the CACNA1A variant (family AR267), but this variant probably occurs de novo, as these are a recurrent cause of CACNA1A-related ataxia." (PMID 35326432, 2022). "Episodic ataxia type 2 is a rare condition, allelic with hemiplegic migraine and spinocerebellar ataxia, caused by an autosomal dominant mutation in the CACNA1A gene resulting in the dysfunction of voltage-dependent calcium channels." (PMID 35897016, 2022). "Mice designed to have a homozygous null mutation in CACNA1A develop severe ataxia, dystonia, and cerebellar degeneration, supporting the notion that mutations in CACNA1A can cause dystonia in humans." (PMID 34395002, 2021). "In our patient, it makes sense that her mutation in CACNA1A would be associated with ataxia, given the importance of CACNA1A channels to normal cerebellar function; it is less intuitive that such a mutation would led to dystonia." (PMID 34395002, 2021).
Ataxia (continued). "In summary, we report a novel CACNA1A variant associated with activity-induced dystonia of the right leg, cervical dystonia, and mild ataxia." (PMID 34395002, 2021). "Only few cases of early onset ataxia, permanent ataxia, or early-onset cerebellar symptoms consistent with congenital ataxia have been associated with (de novo) CACNA1A pathogenic variants." (PMID 33557884, 2021). "This is the second case report of a patient with cervical dystonia and cerebellar ataxia associated with a mutation in CACNA1A." (PMID 34395002, 2021). "CACNA1A variants have been described in several disorders that encompass a wide range of neurologic phenotypes, including hemiplegic migraine, ataxia, cognitive delay, and epilepsy." (PMID 32692472, 2020). "A multi-gene panel sequencing of 118 ataxia genes allowed the identification of a heterozygous mutation c.1913 + 2T > G in CACNA1A, affecting the canonical donor splice site of intron 14 (transcript NM_001127222.1, genomic sequence GL000139)." (PMID 32471306, 2020). "The ataxia is caused by short expansions ranging from 20 to 33 CAGs in the CACNA1A gene, resulting in polyQ expansions in the α1A subunit of P/Q type calcium channel Cav2.1." (PMID 32581696, 2020). "The P/Q channel is widely expressed in the Purkinje and granule cells of the cerebellum, the CACNA1A gene variant is closely associated with cerebellar ataxia." (PMID 33425808, 2020). "Cerebellar ataxia is a common phenotype considering the damage caused by the CACNA1A variant to cerebellar function and/or structure." (PMID 33425808, 2020). "The association of SCN9A with epilepsy and other PE, PEPD, CIP phenotypes resembles the role of CACNA1A in causing discrete phenotypes such as epilepsy, familial hemiplegic migraine, and spinocerebellar ataxia and episodic ataxia." (PMID 32466254, 2020). "Mutation in CACNA1A can lead to spinocerebellar ataxia (SCA) type 6 [SCA6 (MIM: 183086)], episodic ataxia type 2 (MIM: 108500), and familial hemiplegic migraine type 1 (MIM: 141500)." (PMID 31291898, 2019). "In mice, mutations in genes that encode VGCC (Cav2.1) subunits Cacna1a and Cacna2d2 cause neurodegeneration, ataxia and epilepsy." (PMID 30693015, 2018). "Whole-exome sequencing revealed a R583Q missense mutation in the CACNA1A gene in the two most affected persons of this family, i.e., those that had hemiplegic migraine and cerebellar atrophy and ataxia." (PMID 28900389, 2017). "In mice the tottering (tg) mutants have mutations in Cacna1a and exhibit ataxia, motor seizures and cerebellar degeneration." (PMID 28742085, 2017). "Similar cases of a relatively long history of cerebellar ataxia, cognitive impairment and paroxysmal episodes are reported in the literature due to CACNA1A mutations." (PMID 28132242, 2015). "To assess whether this approach could recapitulate known ataxia phenotypes resulting from PC-specific loss of function of Cacna1a, we assessed a battery of behaviors before and for 5 weeks after AAV administration (bottom)." (PMID 40113953, 2026). "CACNA1A encodes the pore-forming α1A subunit of the CaV2.1 calcium channel, whose altered function is associated with various neurological disorders, including forms of ataxia, epilepsy, and migraine." (PMID 40514452, 2025). "Loss- or gain-of-function mutations in the CACNA1A gene, encoding the α1A (Cav2.1) P/Q-type Ca2+ channel subunit, may lead to ataxia, hemiplegic migraine, epilepsy, or cognitive disability." (PMID 40470204, 2025). "Overall, tottering mice provide critical insights into how mutations in the Cacna1a gene and P/Q-type calcium channels contribute to complex neurological disorders such as ataxia, epilepsy, migraines, and other syndromes involving dysregulated neuronal signaling." (PMID 39452036, 2024).
Ataxia (continued). "Recent findings indicate that Cav2.1 channel deficiency due to loss-of-function mutations in human CACNA1A can cause a variety of cognitive impairments and epileptic manifestations, such as cerebellar ataxia, intellectual disability, and childhood-onset refractory epileptic encephalopathy." (PMID 37007007, 2023). "Experiments in animals showed that Cacna1a knockout caused ataxia and epilepsy seizures." (PMID 35600082, 2022). "Deletion mutations of CACNA1A also show impairment in firing regularity in cerebellar vermis, and when firing regularity is restored, this is associated with a reduction of ataxia." (PMID 36078147, 2022). "Her paroxysmal dystonia is likely due to her mutation in CACNA1A, as it is sometimes seen during episodes of ataxia in EA2, there are other case reports of CACNA1A mutations being associated with dystonia, and CACNA1A knockout mice (CaV2.1−/−) exhibit dystonia and cerebellar atrophy." (PMID 34395002, 2021). "Interestingly, ataxia was present in the boy only, and ataxia was markedly worsened when valproate was temporarily applied, resembling absence epilepsy with ataxia (AEA) due to loss-of-function mutations in CACNA1A." (PMID 33802230, 2021). "One hint could come from the finding that Purkinje cell-specific Cacna1a knockout is sufficient to cause cerebellar ataxia in mice." (PMID 33746731, 2021). "EA is a clinically heterogeneous disorder characterized by recurrent spells of ataxia lasting minutes to hours which has been associated over time to a number of genes besides CACNA1A and KCNA1 (CACNB4, SLC1A3, FGF14, SLC2A1, ATP1A3, PRRT2) accounting for the majority of cases." (PMID 32823520, 2020). "CACNA1A variants have been reported in patients with episodic ataxia and spinocerebellar ataxia; however, in this patient, the initial targeted diagnostic screens prior to ES had focused on respiratory chain defects and common mitochondrial mutation analysis (including m.3243A>G, m.8993 T>C, POLG)." (PMID 31345272, 2019). "Thus, FHM relates to gain-of-function mutations on CACNA1A, while ataxia is associated with the alteration of a narrow window of Ca2+ homeostasis in Purkinje cells due to either CACNA1A loss- or gain-of-function mutations." (PMID 29470411, 2018). "The severe early-onset ataxias seen in these patients are similar to reports of severe early-onset ataxia associated with CACNA1A missense variants observed in the S4 transmembrane segment of domain III (e.g. p.I1342T, p.V1396M, and p.R1352Q) or domain IV (R1664Q)." (PMID 28742085, 2017). "Mutations in the CACNA1A gene, encoding the pore-forming CaV2.1 (P/Q-type) channel α1A subunit, result in heterogeneous human neurological disorders, including familial and sporadic hemiplegic migraine along with episodic and progressive forms of ataxia." (PMID 26716990, 2015). "Several HM-linked CACNA1A gain-of-function mutations also produce permanent cerebellar symptoms ranging from slowly progressive cerebellar ataxia and/or nystagmus (with cerebellar atrophy in some cases) or permanent ataxia to early-onset cerebellar signs consistent with congenital ataxia." (PMID 26716990, 2015). "Homozygous CACNA1A –/– loss-of-function mutant mice display severe forms of ataxia." (PMID 24592212, 2014). "These are plausible candidate genes since Grm1 is a known mouse ataxia gene, and Cacna1e encodes a subunit of an R-type calcium channel, while mutations to the related protein family member Cacna1a, encoding a subunit of an L-type calcium channel, causing spinocerebellar ataxia." (PMID 23028291, 2012). "Besides the classical phenotype, mutations on CACNA1A gene are associated with a broader spectrum of clinical features including cerebellar ataxia, making FHM1 a complex channelopathy." (PMID 22527033, 2012).
Ataxia (continued). "Additional support for discrete phenotypes resulting from the same ion channel protein comes from the identification of SCN1A mutations in either epilepsy or familial hemiplegic migraine, and CACNA1A mutations in familial hemiplegic migraine, episodic ataxia and spinocerebellar ataxia." (PMID 19763161, 2009). "Additionally, spinocerebellar ataxia, an inherited progressive disorder affecting coordination and movement, and early infantile epileptic encephalopathy, a severe epilepsy disorder that begins in infancy, have been attributed to CACNA1A gene variants." (PMID 40111503, 2025). "The pathogenic variant in CACNA1A (c.C835T, p.R279C) has been documented to result in diverse manifestations among carriers, ranging from severe epileptic encephalopathy to episodic ataxia and cerebellar ataxia with intellectual deficiency, highlighting significant incomplete penetrance." (PMID 38689878, 2024). "According to the OMIM database, variants in the CACNA1A gene cause “Developmental and epileptic encephalopathy 42,” “Episodic ataxia, type 2,” “Migraine, familial hemiplegic, 1,” “Migraine, familial hemiplegic, 1, with progressive cerebellar ataxia,” and “Spinocerebellar ataxia 6” diseases." (PMID 38587696, 2024). "However, in EA2, point mutations in CACNA1A lead to early onset of episodes of unsteady gait, slurred speech, and incoordination, in infancy or childhood and sometimes accompanied by progressive ataxia between episodes and variable late cerebellar atrophy." (PMID 35757096, 2022). "Cacna1a is broadly expressed in the brain, and global knockout leads to dystonia, ataxia, cerebellar degeneration, absence seizures and early lethality." (PMID 40113953, 2026). "Both ubiquitous and PC-specific Cacna1a disruption also recapitulated several hallmarks of ataxia: reduced locomotion in an open field; impairments in skilled motor behavior, as assessed by narrowing beam crossing; reduced limb strength; and gait deficits." (PMID 40113953, 2026). "CACNA1A-related disorders constitute a diverse group of neurological conditions, including ataxia, migraine, and epilepsy." (PMID 41576935, 2026). "This study design was motivated by the overlapping clinical presentation of specific CACNA1A disease phenotypes with GAA-FGF14 ataxia." (PMID 41240219, 2025). "While homozygous Cacna1a ablation results in severe ataxia, seizures, and premature mortality, mice carrying a heterozygous deletion lack any readily apparent phenotype." (PMID 40127100, 2025). "Background and aims: CACNA1A variants and GAA‐FGF14 ataxia share overlapping neurological phenotypes, including chronic cerebellar signs and episodic ataxia." (PMID 40542581, 2025). "To date, genetic variants of CACNA1A have been associated with several neurological disorders, including FHM1, epilepsy, cerebellar ataxia, dystonia, and cerebellar atrophy." (PMID 40869402, 2025). "Cerebellar ataxia frequently results from ion channel dysfunction, with CACNA1A- and GAA-FGF14-related diseases representing two of the most prevalent genetic etiologies." (PMID 41240219, 2025). "Another more frequent ataxia due to defects in a calcium channel is SCA6, caused by mutations in CACNA1A." (PMID 38003592, 2023). "In a cohort of CACNA1A-positive infantile-onset disorders, nearly all had congenital cerebellar ataxia or paroxysmal events, frequently with cognitive disorders, followed by epilepsy and cerebellar atrophy after age two." (PMID 37008993, 2023). "Imaging studies show that, differently from other ataxias, CACNA1A disorders display a mostly moderate cerebellar atrophy, which is usually more prominent—or event limited—to the vermis." (PMID 34755206, 2022). "Secondary to the atrophy of the cerebellum, patients develop ataxia; PMM2-CDG is associated with the CACNA1A gene gain-of-function mutation that encodes the voltage-gated CaV2.1 channel." (PMID 36295831, 2022).